RPS14 (ribosomal protein S14)
Diseases named in the same sentence as RPS14 in open-access papers (continued):
Sharing a sentence is not in itself a finding about the gene and the disease.
ependymoma (1 paper, 2023). A WHO grade II, slow growing tumor of children and young adults, usually located intraventricularly. "Therefore, we focused on comparing the overlapping clusters between normal and tumor and identified tumor-specific genes such as CASC15 and microRNA MIR99AHG in neuron-like ependymomas and RPS14 and RPS8 in glia-like ependymomas." (PMID 37095395, 2023).
hearing loss (1 paper, 2023). "Due to the high transduction efficiency of AAV‐ie on the human supporting cells, AAV‐ie‐mediated gene regulation, such as Rps14, might be a promising treatment for hearing loss in clinical based on hair cell regeneration." (PMID 36977657, 2023).
leukopenia (1 paper, 2021). "Moreover, these two models showed different MDS phenotypes: JUN mice mainly showed leukopenia, while the reticulocyte count of Rps14 haploinsufficient mice decreased precipitously." (PMID 34179724, 2021).
lung fibrosis (1 paper, 2020). "ZnO specific gene signature further englobed the overexpression of Pla2g16 (FC + 7) a membrane damage sensor; S100a4 (FC + 7) involved in macrophage-induced lung fibrosis; Rps14 (FC + 6), Rps27 (FC + 5), and Mrps15 (FC + 5), three protein synthesis regulators." (PMID 31352547, 2020).
lung squamous-cell carcinoma (1 paper, 2022). "Additionally, RPS14 was identified as one of the reference genes for qRT-PCR in lung squamous-cell carcinoma by RNA-Seq." (PMID 36059657, 2022).
ovarian carcinoma (1 paper, 2025). A malignant neoplasm originating from the surface ovarian epithelium. "Several hub genes, such as RPL11, RPS4X, EIF3I, and RPS14, have been previously linked to various cancers and were confirmed to play crucial roles in ovarian cancer through this study." (PMID 39891297, 2025). "Research into RPS14-targeted therapies could offer new insights for enhancing treatment outcomes in ovarian cancer patients." (PMID 39891297, 2025).
pulmonary hypertension (1 paper, 2022). Increased pressure within the pulmonary circulation due to lung or heart disorder. "To further investigate the relationships among the SRP-DGs and risk of SSc-PH, we constructed a nomogram model using seven SRP-DGs (RPL32, RPS12, RPS14, RPS23, RPS3, RPS7, and SRP9) to predict the risk of pulmonary hypertension complications in patients with SSc." (PMID 36518216, 2022).
infection (32 papers, 2008 to 2025). The state of being infected such as from the introduction of a foreign agent such as serum, vaccine, antigenic substance or organism. "Human cytomegalovirus (HCMV) infection raises the host’s cellular level of uS11/RPS14 and its interaction with MDM2." (PMID 39766272, 2024). "The efficiency of Rps14 infection in the proliferation assay was about 37.5% in control and 37.6% in AAV‐Rps14." (PMID 36977657, 2023). "Once we confirmed the decrease in RPS14 expression by Western blotting, both at 24 h and 48 h post infection (p.i.), we evaluated the anti-HAdV activity of these molecules." (PMID 38273842, 2023). "In contrast, the biological processes downregulated with infection include ribosomal biogenesis (Rpl3, Rpl37, Rps5, Rpl11, Rplp1, Rpl28, Rpl19, Rps28, Rps14)." (PMID 35789215, 2022). "Cell viability was similar between control transduced and sh-RPS14 cells during infection and drug treatment." (PMID 27336364, 2016). "RPS14 showed higher transcript levels upon hormonal treatment and pathogen infection." (PMID 35850621, 2022). "In both cell densities, RPS14 ubiquitination mildly increased with infection." (PMID 27336364, 2016). "Later during infection, RPS14 relocalized to the cytoplasm, was ubiquitinated and degraded." (PMID 27336364, 2016). "Therefore, infection facilitates nuclear translocation of RPS14 by emetine." (PMID 27336364, 2016). "We observed that under all the conditions tested (mock infection, 6 hpi, and 18 hpi), cytoplasmic ribosome proteins from the small (RPS6, RPS14, and RPS3) and large (RPL23a, RPL24, and RPL8) subunits were enriched in the ASFV-DP fraction." (PMID 29021398, 2017). "HCT-116 infection with RPL27A-sh2 induced significant increases in cells at the early stage of apoptosis (55%), as was the case with RPS14 (40%) and RPL5 (35%) knockdown." (PMID 27374104, 2016). "We found that ribosomal proteins, such as ribosomal protein S20 (RPS20), S14 (RPS14), L15 (RPL15), and S14 precursors, which are generally expressed in bradyzoites, were highly expressed in the ME49 strain 72 h post-infection, indicating bradyzoite formation in the brain organoids." (PMID 32820712, 2020). "Irrespective of cell density, emetine induced RPS14 translocation into the nucleus during infection." (PMID 27336364, 2016).
tumor (25 papers, 2010 to 2026). "To gain deeper insights into the physiological changes associated with RPS14 upregulation, we performed proteomics analysis of tumor tissues from PBS- and F. nucleatum–treated WT, VillinCreER2Ly6afl/fl, and Ly6aCreER RPS14fl/fl mice." (PMID 39656543, 2025). "This work provides diverse insights into how F. nucleatum drives the transformation of LY6A+ stem cells into tumor stem cells through the upregulation of RPS14, a ribosomal protein linked to abnormal stem cell proliferation and tumorigenesis." (PMID 39656543, 2025). "This suggests that RPS14 played a key role in facilitating the tumor-promoting effects of F. nucleatum." (PMID 39656543, 2025). "Patients with elevated F. nucleatum infection, determined via metagenomic analysis of stool samples, had a prominent positive correlation between F. nucleatum infection levels and RPS14 expression within tumor tissues." (PMID 39656543, 2025). "Further investigation using F. nucleatum–exposed Ly6aCreERT2 H11G/R mouse models revealed a similar upregulation of RPS14 expression in LY6A+ RSCs within tumor tissues." (PMID 39656543, 2025). "Our results further demonstrated that specific RPS14 ablation in LY6A+ stem cells greatly attenuated the tumor-promoting effects of F. nucleatum, resulting in a substantial reduction in tumor burden within the colon." (PMID 39656543, 2025). "It not only strengthens the evidence for LY6A+ stem cells as tumor-initiating cells but also identifies RPS14 as a new signaling molecule driving this transformation." (PMID 39656543, 2025). "This evidence suggests the emergence of a complete timeline in human samples, tracing the progression from F. nucleatum infection to RPS14 upregulation and subsequent tumor development." (PMID 39656543, 2025). "Additional experiments in several mouse models demonstrated that specific Ly6a KO in the intestine, LY6A+ cell ablation, or Rps14 KO in LY6A+ cells led to a noted reduction in RPS14 expression and tumor cell proliferation." (PMID 39656543, 2025). "Of the candidate genes, haploinsufficiency was evident in secreted protein acidic and rich in cysteine (SPARC), a tumor suppressor gene, and ribosomal processing S14 gene [RPS14 (component of 40S ribosomal subunit)]." (PMID 25295231, 2014). "Tumor-suppressing effects of RPS14 have been studied in previous research." (PMID 39891297, 2025). "F. nucleatum triggers LY6A+ tumor stem cells through upregulation of RPS14 expression." (PMID 39656543, 2025). "Additionally, human samples and transcriptomics analyses revealed that F. nucleatum infection upregulated RPS14 expression in tumor tissues, further supporting the role of the F. nucleatum/RPS14 axis in human CRC." (PMID 39656543, 2025). "Importantly, L y6a or Rps14 KO clearly attenuated these F. nucleatum–mediated processes, confirming the critical role of RPS14 in the tumor-promoting effects of F. nucleatum." (PMID 39656543, 2025). "Considering the correlation between high RPS14 expression and tumor stem cell proliferation, we speculated that KO of RPS14 may inhibit tumor growth by halting progression at the small adenoma stage." (PMID 39656543, 2025). "Moreover, analysis of clinical CRC cohorts revealed a strong correlation between F. nucleatum infection, RSC expansion, and elevated RPS14 expression in tumor tissues." (PMID 39656543, 2025). "Notably, RPS14 expression was obviously elevated in LY6A+ RSCs derived from F. nucleatum–treated tumor tissues." (PMID 39656543, 2025). "Recent studies would indicate that the ribosomal protein (RP) coding gene Rps14 identified in this study may also perform tumor suppressor functions in a preleukemia syndrome in humans." (PMID 21170304, 2010). "Similarly, we validated the tumor-suppressive RPS14 editing in HCT116 colon cells." (PMID 36969056, 2023).
tumor (continued). "To further confirm that F. nucleatum mediates tumor stem cell initiation and progression through RPS14 upregulation in LY6A+ RSCs, we generated Ly6aCreER RPS14fl/fl mice to achieve conditional KO of RPS14 in LY6A+ cells." (PMID 39656543, 2025). "Specifically, during F. nucleatum infection, activation of RPS14 in LY6A+ cells appeared to trigger a shift toward abnormal hyperproliferation, transforming these regenerative cells into tumor-initiating stem cells." (PMID 39656543, 2025). "Lastly, we validated the expression of the five RBRS genes (RPL38, RPS2, RPS14, RPS19, and RPS28) using qRT-PCR on tumor and adjacent normal samples from 12 ccRCC patients at Meizhou Hospital." (PMID 40642093, 2025). "coli), RPLP0 (tumor progression, invasion, metastasis), RPS5, RPL9, RPS14, RPS2, RPL3, and RPL23." (PMID 34445327, 2021). "However, we also observed that the increase in tumor number induced by F. nucleatum was not completely abolished after RPS14 KO in LY6A+ cells." (PMID 39656543, 2025). "Furthermore, we observed that the upregulation of ERK1/2 phosphorylation in RPS14+ regions (data not shown), along with increased KI67 expression, promoted cell proliferation, reinforcing the role of RPS14 in tumor development." (PMID 39656543, 2025).
cancer (17 papers, 2016 to 2025). A tumor composed of atypical neoplastic, often pleomorphic cells that invade other tissues. "Moreover, other genes upregulated in distinct but also specific stimuli like PPA1, GADD45B, C1D, TRPV2 and RPS14 were associated with DDR, cancer and apoptosis." (PMID 39623312, 2024). "Overexpression of RPS14 can inhibit Rb phosphorylation and induce cell cycle arrest and aging, which may be related to cancer treatment." (PMID 33305312, 2021). "Additionally, RPS14 can inhibit the activity of cancer-promoting proteins like c-Myc." (PMID 39891297, 2025). "Recently, several RPs, including RPL5, RPL11, and RPS14, have been found to associate with TAp73, but not ΔNp73, to overcome MDM2-mediated inactivation, leading to TAp73-induced cancer cell apoptosis." (PMID 32198344, 2020). "Finally, we showed that the relative proportion of sites with increased vs. decreased editing levels could be partially explained by the differential expression of three RNA binding proteins – RPS14, SRSF9 and DHX15 – in a subset of the cancer types we analyzed (Supplementary Results)." (PMID 26980570, 2016).
hematologic malignancies (2 papers, 2022 to 2025). "RPS14 is considered to be associated with the 5q-syndrome and some kinds of hematologic malignancies." (PMID 36059657, 2022). "Although the role of RPS14 in hematologic malignancies has been widely reported, there are few studies investigating the association between RPS14 and solid cancers." (PMID 36059657, 2022).
adenocarcinoma (1 paper, 2007). A common cancer characterized by the presence of malignant glandular cells. "Similarly, in adenocarcinomas of the colon, the expression of RPLP0, RPS14 and GAPDH varied between primary tumors and corresponding resection margins." (PMID 17640361, 2007).
RPS14 also shares sentences with these, for which no sentence is quoted: Shwachman-Diamond syndrome (2 papers); acute myeloid leukemia (1); amyotrophic lateral sclerosis (1); asplenia (1); astrocytoma (1); bone marrow failure (1); dyskeratosis congenita (1); escherichia coli infection (1); genetic disorder (1); hepatocellular carcinoma (1); herpes infection (1); HIV-1 infection (1); liver cancer (1); melanoma (1); microcephaly (1); osteosarcoma (1); prostate carcinoma (1); rectal cancer (1); refractory anemia (1); Salmonella Infections (1); schizophrenia (1); Stroke (1); tauopathies (1); Treacher-Collins syndrome (1); triple-negative breast carcinoma (1).